EGFR (epidermal growth factor receptor)
Diseases named in the same sentence as EGFR in open-access papers (continued):
Sharing a sentence is not in itself a finding about the gene and the disease.
tumor (continued). "As an example, formalin fixed, paraffin embedded (FFPE) tumor DNA preserved in tissue blocks at the time of diagnosis may not be representative of targetable genomic alterations (such as EGFR T790M) developing weeks to months post-biopsy through tumor genome evolution." (PMID 33004033, 2020). "Both mutation status and tumor sidedness may impact survival and disease progression and RAS mutation status has been shown to predict response to anti‐epidermal growth factor receptor (EGFR) therapy." (PMID 31856410, 2020). "Similar analyses from the BEACON-trial investigating a targeted combination therapy with BRAF-, MEK-, and EGFR inhibition in BRAF-MT mCRC patients could clarify to which extent tumor dynamics observed in the VOLFI trial are also evident with targeted tumor therapy." (PMID 32449003, 2020). "At all doses, the free EGFR in the stroma-rich areas (as indicated by the dash lines) was suppressed to a higher degree, primarily because of a relatively lower fraction of EGFR-positive tumor cells and a tighter antibody-EGFR binding in the stromal-rich tumor areas." (PMID 33028895, 2020). "We also observed a down-regulation in the expression of ABCG2 transporter and epidermal growth factor receptor (EGFR) in tumor cells by Western blot, after PX plus carbachol or APE administration revealing that both proteins could be involved in the mechanism of action of this treatment." (PMID 32911509, 2020). "We assume that in smoking NSCLC patients, EGFR mutation is not the key driver, and the EGFR mutant subclone might present at a low fraction in the tumor content." (PMID 32746896, 2020). "This may capture intratumoral transcriptomic heterogeneity in CRCs with more than one subtype signature coexisting in the same tumor and improve assessment of prognosis and its association with RAS/BRAF wild-type statuses and tumor sidedness in patients with mCRC treated with anti-EGFR therapy." (PMID 33015526, 2020). "However, a sustained inhibitory effect was observed for A498 cells suggesting that inhibition of the EGFR pathway may hold some benefit depending on the genetic characteristics of the tumor." (PMID 31938054, 2020). "Therefore, combination therapy strategy targeting the c-Met and EGFR pathway may bring more significant anti-tumor effect." (PMID 33195182, 2020). "Because in tumor cells protein fucosylation could be increased, and because N-glycans of EGFR are also fucosylated, we analyzed whether this modification was also affected in EGFR of shGOLPH3 cells." (PMID 33238647, 2020). "Based on the responses of the microbial communities to current individualized drug therapies, including the currently prevalent chemotherapies using targeted drugs for VEGF and EGFR, we hypothesized that the flora found at different tumor sites will affect the clinical treatment decisions." (PMID 33324571, 2020). "In addition, SPP1 may also affect the immune escape and malignant biological behavior of tumor cells by regulating EGFR activation." (PMID 32815653, 2020). "Since EGFR is also expressed on normal cells, it cannot be excluded that the treatment of PCa patients with our targeted toxins could lead to side effects due to on-target/off-tumor activities." (PMID 33260619, 2020). "Liquid biopsy can be utilized to dynamically detect resistance mutations in course of treatment with EGFR inhibitors and, when the tumor tissue biopsy is not possible, ctDNA analysis is the only available method for the identification of patients that can benefit from a TKI therapy." (PMID 36046387, 2020). "Their direct effect on MAPK pathway, EGFR transactivation and Protein kinase C and D pathway activation makes them an interesting target in therapeutic use in the subset of cancers which express NT and/or its receptors, making way for a promising new tumour agnostic drug." (PMID 32336282, 2020).
tumor (continued). "In fact, the results of our IPA analysis are consistent with these previous studies, which suggest the possibility that Ambrisentan’s inhibitory effects could also involve other tumor-promoting signalling pathways (e.g. EGFR) and transactivation signalling events." (PMID 32985601, 2020). "However, only 40–60% of patients with wild type KRAS tumours respond to anti EGFR therapy." (PMID 32594310, 2020). "Furthermore, CCND1 and EGFR show an additive effect on OSCC tumor progression." (PMID 33317149, 2020). "EGFR stands in the centre of carcinogenesis also at the EV level, both as a key membrane protein involved in the transfer of information between parental cancer cells and various bystander cell types in the tumoural microenvironment, and by inducing EV secretion in a variety of contexts." (PMID 33302515, 2020). "Thus, the precise role of EGFR in tumor development is difficult to unravel." (PMID 32413049, 2020). "Therefore, EGFR works as both a signal transducer, as well as a so-called tumor marker." (PMID 32878053, 2020). "In the initial index patient’s tumor, WES analysis revealed amplification of chromosome 7 and deletion of chromosome 10 and focal deletion of CDKN2A locus on chromosome 9 along with an activating ectodomain EGFR A289V mutation, suggesting that the tumor cells had undergone chromothripsis." (PMID 31376079, 2020). "On the other hand, 16 patients were diagnosed with EGFR T790M mutation from the tumor samples by both PANAMutyper and cobas v2 but did not receive osimertinib treatment, including three patients who had early-stage disease without progression and 13 patients with late stage disease." (PMID 32224854, 2020). "Probably as a result of the tumor selectivity, depatuxizumab mafodotin did not cause dose-limiting dermatological adverse events or diarrhea characteristic of other anti-EGFR therapies, even though EGFR is broadly expressed in normal tissues." (PMID 32111076, 2020). "Since tumor heterogeneity results from genomic inhomogeneity and evolution of clones, targetable EGFR mutation may co-exist with non-targetable mutations such as T790M." (PMID 33370365, 2020). "In summary, we herein examined subcellular EGFR interactomes, analyzed the putative functions of EGFR at these subcellular locations, and report that a nuclear EGFR-interacting protein selected for further study, hnRNP A3, modulates nuclear EGFR accumulation and tumor growth in NSCLC." (PMID 32321917, 2020). "However, a Kaplan–Meyer analysis based on EGFR expression of metastatic tumor tissues demonstrated that at both sides low EGFR-HS patients are characterized by a nominally better median OS (left side low: 766.5 days versus high: 368 days, right side low: 283.5 days versus high: 55 days)." (PMID 32155907, 2020). "In both cases, the clinical course and previous genetic findings suggest that both EGFR T790M mutations emerged in metastatic lesions that were not captured by tumor biopsies, illustrating the potential of ctDNA for the characterization of tumor heterogeneity." (PMID 32748806, 2020). "However, except from a handful of known genetic aberrations such as EGFR mutations and anaplastic lymphoma receptor tyrosine kinase (ALK) rearrangement, no subgroups of NSCLC are stratified for optimized treatment based on the molecular profile of the tumor." (PMID 33324562, 2020). "Moreover, activating EGFR in the head and neck CSCs enhanced expressing the genes engaged in the CSC rapid growth or proliferation (OCT4, BMI1, CD44, NANOG) and CSCs treatment through inhibiting EGFR declined the tumor growth and augmented the sensitivity to cisplatin." (PMID 32280305, 2020). "Tumor expression of programmed death ligand-1 (PD-L1) has been shown to be associated with the efficacy of immune checkpoint inhibitors in patients with non-squamous NSCLC, whereas immune checkpoint inhibitors are known to be less effective in patients with EGFR-mutant NSCLC." (PMID 33255696, 2020).
tumor (continued). "First- or second-generation EGFR tyrosine kinase inhibitors (EGFR-TKIs) (e.g., erlotinib, gefitinib, and afatinib), administered to patients whose tumors harbor these genotype alterations, led to marked tumor response and improved progression-free survival and quality of life over chemotherapy." (PMID 33282740, 2020). "While acquired resistance limits the clinical benefit of cetuximab currently, an improved understanding of the impact of cetuximab on immune recognition of EGFR-expressing tumor cells may lead to development of novel therapeutic combinations for treating HNSCC patients." (PMID 33281820, 2020). "We hypothesize that passive targeting of P-GE11-Cy7 with a molecular weight close to the limit of the renal filtration is highly elevated and, in combination with the slightly pronounced active EGFR-targeting, leads to the observed tumor accumulation after 24 h." (PMID 31906300, 2020). "Another factor that could result in some biopsies having only EGFR and others only PDGFRA amplified is that the mutations occurred in different places, resulting in the populations occupying different, spatially separated regions of the tumour." (PMID 33120534, 2020). "Due to tumor heterogeneity, the EGFR T790M mutation might not be found in all tumor sites, so it is not totally helpful in case of disease progression." (PMID 36046486, 2020). "As HGK is able to inhibit the tumor growth of TKI-resistant NSCLC cells, the potential inclusion of HGK as an adjuvant drug in the treatment of NSCLC patients harboring activating EGFR mutations might be explored." (PMID 32093124, 2020). "IRE1α-XBP1s pathway might involve in EGFR driven tumor cell proliferation." (PMID 32489465, 2020). "Furthermore, expression of a constitutively active form of EGFR, EGFRλ, leads to the formation of tumours that display the same hallmarks as in RasV12 induced tumours, showing that overactivated EGFR can induce basal extrusion of epithelial cell in the accessory gland." (PMID 32385236, 2020). "Therefore, it is of significant interest to determine whether psid inactivation can inhibit EGFR signaling-induced tumor growth." (PMID 32559195, 2020). "Interestingly, PTPN12 acts as a tumor suppressor which regulates the activities of multiple oncogenic tyrosine kinases, including EGFR, human epidermal growth factor receptor 2 (HER2), and platelet-derived growth factor receptor-β (PDGFRβ), and its deficiency is identified in several carcinomas." (PMID 33050232, 2020). "Inter-tumor heterogeneity may hinder the therapeutic efficiency of anti-EGFR treatments." (PMID 31181806, 2019). "Additionally MPC1 was negatively correlated with tumor size and TNM stages, but not related with tumor location, histological grade, EGFR mutation." (PMID 30770798, 2019). "NSCLC patients with EGFR-activating mutations in their tumours had significantly higher plasma levels of miR-504 compared to those with wild-type EGFR, regardless of the normalisation approach used (p = 0.0072 for miR-191-normalised data; p = 0.0236 for miR-16-normalised data)." (PMID 30953094, 2019). "In addition, we analyze how strategies aiming to enhance the favorable effects in the tumor microenvironment may contribute to overcome resistance to EGFR therapies." (PMID 31370270, 2019). "The delineation of specific oncogenic pathways has allowed stratification of tumours and incorporation of patient-specific targeted therapy based on, for example, the activation status of receptor tyrosine kinases such as epidermal growth factor receptor (EGFR)." (PMID 30845770, 2019). "However, androgen receptors are found in 80 to 90% of SDC, as well as 30 to 70% expressing the human epidermal growth factor receptor (EGFR) and Her2neu, making the tumor a target for androgen deprivation therapy and monoclonal antibodies like cetuximab or trastuzumab, respectively." (PMID 31921675, 2019).
tumor (continued). "Overall, these findings suggest that downregulation of miR-27a promotes tumor growth and metastasis via targeting EGFR and its downstream NF-κB signaling pathway, reminding that miR-27a plays a vital role in the progression of cSCC and could be a new therapeutic target." (PMID 32039029, 2019). "It is unclear, however, whether AXL is an inducer or effector of the EMT process and whether AXL inhibition, combined with an EGFR-TKI, is able to overcome the acquired resistance to EGFR-TKIs induced by EMT, a feature that may be closely associated with tumor heterogeneity." (PMID 30651547, 2019). "Furthermore, the silica nanoparticles bind to expressed EGFR of the tumor cells in a short time." (PMID 31561451, 2019). "Therefore, we tested tumor-specificity on physiologically EGFR-expressing fetal human astrocytes." (PMID 31903167, 2019). "Likewise, four tumor‐derived EGFR variants W731R, P741S, N196D, and I938M also failed to drive the IL‐3‐independent growth of Ba/F3 cells." (PMID 31314158, 2019). "In addition, to test the therapeutic effect of targeted sumIL-2 therapy, we also generated mouse tumor cell lines preferentially expressing mouse EGFR with few site mutations which can be recognized by Cetuximab, the FDA-approved anti-human EGFR antibody for proof of concept of tumor targeting." (PMID 31462678, 2019). "In the sample from relapsed tumor, there exist some large signals for EGFR, CDK6, and MYC along with the widely distributed smaller signals consistent with eccDNA; therefore, we cannot rule out the possibility that HSR may co-exist with double minutes at this time." (PMID 30267146, 2019). "Finally, in HLA-E+ tumors, expressing tumor-associated antigens, NKG2A blockade could increase the therapeutic efficacy of other mAbs (for example, anti-EGFR mAb), favoring the NK cell triggering via the CD16-mediated antibody-dependent cytotoxicity (ADCC)." (PMID 32010130, 2019). "However, more complex mechanisms involving the interaction of CRC cells with tumor microenvironment might also play a relevant role in determining the sensitivity/resistance of CRC to anti-EGFR MoAbs." (PMID 31226844, 2019). "However, we have shown that the concentrations of AXL and GAS6 in plasma were not correlated with the corresponding expression levels in tumor tissue of NSCLC patients harboring EGFR activating mutations." (PMID 31419057, 2019). "Together with others, we have demonstrated that the combination of AKT and EGFR inhibitors could be of benefit in patients with EGFR mutations, however, even when blocking AKT, tumor regrowth could occur through the activation of other downstream regulators, via Src/FAK." (PMID 31660987, 2019). "According to phospholipids imaging, the EGFR mutation spatial distribution map in whole tumor tissues was not difficult to generate, thereby we could visually observe the EGFR mutations spatial distribution features." (PMID 31555581, 2019). "Our results demonstrate that noninvasive molecular imaging of EGFR may open the door to guiding the selection and monitoring of anti-EGFR targeted therapy before it is possible to detect tumor response by changes in volume on conventional cross-sectional imaging modalities." (PMID 30213849, 2019). "EGFR could be used as a promising biomarker for predicting pituitary corticotroph tumor recurrence." (PMID 31798535, 2019). "In contrast, the overall agreement ranged in 63–100% in activating EGFR mutations, which may reflect the difference of tumor heterogeneities rather than assay sensitivity between activating mutations and acquired mutations." (PMID 31217900, 2019). "Mechanically, DCN binds to EGFR/ErB2 extracellular functional domains and triggers mitogen-activated protein kinase activation and the increase of cytosolic Ca2+, which accelerates cell cycle arrest and induces intrinsic cell apoptosis, eventually leading to tumor cell growth inhibition." (PMID 31583243, 2019).
tumor (continued). "Importantly, the accumulation of 89Zr-DFO-ZEGFR:03115 in the tumor correlated with EGFR protein expression level, assessed ex vivo by tumor tissue lysates and EGFR staining of tumor sections derived from xenograft models with various levels of receptor expression." (PMID 30213849, 2019). "PCC0208027 and other EGFR TKIs showed no anti-tumor activity against A549 cells with KRAS mutation." (PMID 30952931, 2019). "Moreover, anti-CA125, anti-HER2/neu, anti-MUC1, anti-EGFR mAb treatment can circumvent the tolerance to self-antigens expressed on tumor cells as shown by the increase of the frequency of CD4+ and/or CD8+ T cells recognizing peptides derived from the target molecule in cancer patients." (PMID 31494742, 2019). "Targeting EGFR degradation to kill cancer cells, with less destructive effects on normal cells, is an attractive and promising rationale for further investigations aiming to stop metastatic progression and to override the drug resistance in EGFR-driven tumours." (PMID 31374910, 2019). "Over the past five years, we have revealed that EHD1 overexpression in NSCLC predicts poor prognosis for patients and that EHD1 might play a pivotal role in tumor metastasis, stemness, chemotherapy resistance and epidermal growth factor receptor (EGFR)-tyrosine kinase inhibitor (TKI) resistance." (PMID 31023336, 2019). "Therefore, CuB is a novel anti-tumor drug that treats GR NSCLC by inhibiting the EGFR/ERK pathway." (PMID 30759826, 2019). "A defined group of immune-checkpoint inhibitors non-responder tumours carry EGFR (epidermal growth factor receptor) mutations: nowadays, anti-PD-1/PD-L1 clinical trials often do not involve this type of patient and the use of immune-checkpoint inhibitors are under evaluation in this setting." (PMID 31554160, 2019). "In addition, downstream EGFR signal pathways in tumor tissues were assessed." (PMID 30733972, 2019). "Thus, the synergistic anti-tumor effect of rhein (or diacerein) could be useful in overcoming the resistance to EGFR TKIs and sensitize the EGFR targeted therapy for PC." (PMID 30674340, 2019). "Chemotherapeutic drugs can induce apoptosis, leading to a decrease in VEGF secretion and a decrease in VEGFR‐2 expression, thereby inhibiting angiogenesis and further tumor growth, and (ii) EGFR and VEGFR2 may synergistically inhibit tumors by inhibiting the MAPK‐ERK and PI3K‐AKT‐mTOR pathways." (PMID 31486270, 2019). "CTC separation and counting focusing only on positive EpCAM could be one-sided, which could lead to a large amount of tumor cells with other positive markers (such as EGFR positive cells, EMT inverted cells) being ignored, and the sensitivity could be low as well." (PMID 31767014, 2019). "Indeed, EGFR wild type tumor cells were detected in all six tumor samples." (PMID 31014278, 2019). "In addition to the relative abundance of EGFR-mutations and ALK-rearrangements, the levels of phosphorylation of EGFR, ALK, or downstream proteins detectable in tumor samples by IHC have been proposed for predicting the efficacy of TKIs in NSCLC with EGFR/ALK co-alterations." (PMID 31266248, 2019). "In addition, the PD-L1 expression level in tumour cells may also be involved in the objective responses of patients with EGFR+/ALK+ NSCLC." (PMID 31747941, 2019). "These tumor cells may bear some functional resemblance to the environment they are capable of metastasizing with both tumor and neuron being low proliferating with high EGFR expression and increased membrane trafficking." (PMID 31857847, 2019). "In some areas within a tumor, EGFR can be mutated but not amplified." (PMID 31014278, 2019). "Furthermore, EGFR-CPIG NPs were able to accumulate in tumor in an ectopic CRC murine model." (PMID 31662751, 2019).